MIR219A1 (microRNA 219a-1)
Synonyms: hsa-mir-219-1; MIR219-1; MIRN219-1; MRI219-1; hsa-mir-219a-1; mir-219; mir-219a-1
Gene: MicroRNA gene on chromosome 6 (33,207,835 to 33,207,944, forward strand). Ensembl gene ENSG00000199036.
Gene Ontology:
Biological process: miRNA-mediated post-transcriptional gene silencing
Cellular component: RISC complex